IL6 (interleukin 6)
Diseases named in the same sentence as IL6 in open-access papers (continued):
Sharing a sentence is not in itself a finding about the gene and the disease.
cancer (continued). "If the concentrations of plasma IL6 and GDF15 exceed the critical value, positive feedback cycles of inter-BAT mutual activations would be created to induce cancer cachexia as a result of uncontrolled catabolism." (PMID 33182625, 2020). "VEGF and IL‐6 release and aquaporin 4 (AQP4) expression were assessed as indirect markers of cancer‐related angiogenesis and cell invasion, respectively." (PMID 32022398, 2020). "This phenomenon results in increased concentration of numerous cytokines, such as IL-6, IFN-γ, and TNF-α, within the tumor microenvironment and subsequent cancer progression." (PMID 33260925, 2020). "And, IL-6 increases angiogenesis by transcriptional upregulation of VEGF in JAK/STAT3 and hypoxia inducible factor 1α (HIF1α) dependent manner in cancer cells." (PMID 33351844, 2020). "We found that cancer patients with severe and critical ill type showed higher PCT and IL-6 levels than ordinary type, suggesting that overproduction of early response proinflammatory cytokines leading to poor prognosis." (PMID 32766161, 2020). "The levels of inflammatory cytokines, such as IL-6 and TNF-α, increased in patients with poor PS and cancer cachexia." (PMID 32792640, 2020). "For the purpose of correlation analysis we have retrieved data on systemic concentrations of IL-1β, IL-4, IL-6, IL-8, IL-12p70, FGF2, G-CSF, GM-CSF, MCP-1, MIP-1α, PDGF-BB, TNFα, and VEGF-A, available for 43 of our cancer patients." (PMID 33020452, 2020). "The nuclear factor kappa B (NF-κB) signaling pathway and its downstream inflammatory factors interleukin-6 (IL-6), interleukin-1β (IL-1β), and tumor necrosis factor-α (TNF-α) play an important regulatory role in the developmental process of cancer pain." (PMID 32431607, 2020). "IL-6, MCP-1 and VEGF, which are secreted by osteoblasts, enable cancer cells to colonize and proliferate in the bone microenvironment." (PMID 32674405, 2020). "In the cancer cachexia condition, inflammatory factors, such as TNF-α, IL-1, and IL-6, can activate p38 MAPK signaling, thereby inhibiting PGC-1α transcription and reducing energy production." (PMID 33102208, 2020). "IL-6 activates the STAT3 signaling pathway to promote the expression of CD44+ in hepatocellular carcinoma cells and it increases sphere formation when cancer cells are co-cultured with macrophages." (PMID 32326073, 2020). "IL-6 and YKL-40 are both involved in complex immune modulatory systems, cancer propagation, and regulate each other's expression." (PMID 32363159, 2020). "Cytokine/chemokine profiling of these MDSCs demonstrated that both myeloid cell subsets from cancer patients produced substantial amounts of CCL2, CCL3, CCL4, G-CSF, IL-8 and IL-6." (PMID 31811337, 2020). "A recent study has shown that interleukin-6 (IL-6)-mediated STAT3 phosphorylation plays a role in EndMT, thus inducing cancer growth." (PMID 32296578, 2020). "Two hepatokines known to play a role in skeletal muscle homeostasis and pathogenesis of multiple diseases, including cancer cachexia, are the anabolic factor IGF1 and the catabolic factor IL6." (PMID 31915140, 2020). "In summary, this study has shown that TU-100 inhibited the malignant potential of cancer cells by both suppressing HSC activation and secretion of IL-6 from HSCs, and inducing directly the autophagy of cancer cells." (PMID 33346211, 2020). "In fact, in the TME, cancer cells promote TLR2 activation in DCs, which induces the secretion of elevated levels of cytokines including IL-6 and IL-10 and the overexpression of their receptors." (PMID 33321934, 2020). "IL-6 activates the JAK/STAT3 pathway and promotes angiogenesis, invasion, metastasis, and TNF-α activate EMT and promote cancer progression." (PMID 32796516, 2020). "Therefore, targeting of IL-6 signalling may be of therapeutic benefit in several cancers." (PMID 32899142, 2020). "Downstream in the IL-6 signaling pathway, JAK is another important drug target for cancer treatment." (PMID 33322216, 2020).
cancer (continued). "Most relevant are the observations that gal-8 present in serum of cancer patients interacts with blood vascular endothelium and promotes secretion to the circulation of MCP-1, IL-6 and G-CSF." (PMID 32355198, 2020). "The cytokines IL-6 and TNF-α and transcription factors, STAT3 and NFKB contribute to both inflammation and cancer development." (PMID 32731413, 2020). "Mesenchymal stem cells can promote cancer stemness through the NF-kB pathway by secreting CXCL12, interleukin-6(IL-6) and IL-8." (PMID 33233552, 2020). "In vitro condition medium (CM) from LPS-treated macrophages containing IL-1b, IL-6, and TNF-α induced proliferation of HCT116 colon cancer cell line, increased NF-kB activity and VEGF secretion in cancer cells." (PMID 33194645, 2020). "The binding of HA-MITF was nevertheless enhanced in 4C-HA-MITF cells, with multiple MITFBSs in proximity of several of these cancer-relevant genes (e.g., AXL, IL6, TGFBI, and EGFR,) compared to HA-MITF binding in 3C-HA-MITF." (PMID 32605315, 2020). "Interestingly, increased expression of IL-6 has been positively correlated to the increased circulating levels of IL-6, thus suggesting that adipose tissue, particularly subcutaneous adipose tissue, may act as a key source of inflammatory mediators during cancer cachexia progression." (PMID 32660156, 2020). "Increased IL6 expression has been reported to activate STAT3 signaling, subsequently involving drug resistance and cancer progression." (PMID 32963220, 2020). "MSCs promotes tumour growth by increasing the number of cancer stem cells through bone morphogenetic protein signalling and WNT, TGF‐β, IL‐6/JAK2/STAT3 signalling pathways." (PMID 32588948, 2020). "Cell molecules including transcription factors (e.g., NF-κB, STAT3, HIF1α) and cytokines (e.g., IL-6, Cox-2, and TNF-α) coordinate together and lead to the amplification of inflammation and creation of a suitable environment for cancer growth." (PMID 32758196, 2020). "Along with their role in chronic inflammation, IL-6 and TNF-α also contribute to other mechanistic effects on cancer development." (PMID 33261185, 2020). "Cancer-associated adipocytes interact with cancer cells and secrete the inflammatory cytokines, such as IL-6 and TNF-α, which contribute to pro-cancer inflammation that is known to aggravate cancer progression." (PMID 32796516, 2020). "hWJSCs were also shown to release many molecules like IL-6, IL-8, and MCP-1 that are involved in producing DAMPs on cancer cells and modulate the immune response in xenograft animal models of cancer." (PMID 32377203, 2020). "Therefore, antibodies targeting the IL-6 receptor (tocilizumab and sarilumab), IL-6 (siltuximab), and other receptor antagonists (α1-adrenergic receptor antagonist, prazosin) for mitigating cytokine storm are promising therapeutic strategies for the treatment of cancer patients with COVID-1935." (PMID 32944387, 2020). "TNF-α, IL-6 and COX-2 are considered to be important cytokines linking inflammation and cancer, which are also recognized to play an indispensable role in the development and progression of CAC." (PMID 33603669, 2020). "Since CRP is one of the acute phase proteins derived from hepatocytes stimulated by circulating interleukin 6 (IL-6), CRP levels in cancer patients reflect the amount of IL-6 in the circulating blood produced by T-cells or macrophages." (PMID 32567660, 2020). "IL-6 orchestrates the interactions between cancer cells and the TME by preparing the soil for cancer homing at target organs and has been also shown to stimulate immune evasion by inducing the stabilization of programmed death-ligand 1 (PD-L1)." (PMID 33194755, 2020). "Several signaling pathways, including IL‐6/JAK2/STAT3 and TGF‐β/Smad, as well as the crosstalk between them, contributed to EMT and cancer stemness." (PMID 31860165, 2020).
cancer (continued). "Our results, along with the findings of other authors, indicate the ability of the CV extract to induce the production of many cytokines, including IL-1β, IL-2, IL-6, IL-10, TNF-α, and IFN-γ, by immune cells and cancer cells." (PMID 33260615, 2020). "Observe also that 20 (40%) of the illustrated apoptotic genes are synergistically expressed with IL6 in the normal tissue and only two (4%) in the PTC nodule, suggesting the decoupling of the programmed cell death from the inflammatory response in cancer." (PMID 32887258, 2020). "Some of the vital CAF-activating factors released by cancer cells are TGF-β, PDGF, IL-6, IL-1β, epidermal growth factor (EGF), and lysophosphatidic acid (LPA)." (PMID 33066013, 2020). "IL-6 activates signal transducer and activator of transcription 3 (STAT3), which is crucial for proliferation of cancer cells." (PMID 33351844, 2020). "Dysregulation of circulating inflammatory markers and cytokines such as interleukin-1 receptor antagonist (IL-1RA), interleukin-6 (IL-6) and C-reactive protein (CRP) has been reported in cancer patients and survivors experiencing CRF." (PMID 33187543, 2020). "The molecules that participated in this mechanism included CXCL12, IL-6, annexing II and VEGF, as they contributed to both HSC and cancer cells’ infiltration and survival." (PMID 32742634, 2020). "In this context, the synthesis and secretion of cytokines like interleukin-6 (IL-6), a potent STAT3 activator, have been reported in response to cytotoxic damage in cancer cells." (PMID 33023532, 2020). "IL-6 induces EMT, thus increasing the CSC pool by promoting the transformation of more differentiated cancer cells into CSCs." (PMID 33321934, 2020). "Co-culturing GC cells with bone-marrow-derived myofibroblasts (BMFs) has shown high expression of IL-6 and hepatocyte growth factor (HGF) secreted by BMFs, which mediated the secretion of TGF-β1 by the surrounding cancer cells." (PMID 32268527, 2020). "Results showed that aHSCs in cancer-CM significantly increased messenger RNA (mRNA) expressions of α-SMA and IL-6." (PMID 33346211, 2020). "Inflammation plays a supportive role in facilitating this process, TNF in the microenvironment stimulates the release of pro-angiogenic factors IL-6, IL-8, TGF-β, and vascular endothelial growth factor (VEGF) by cancer cells via the induction of NF-κB." (PMID 33076397, 2020). "Coincidentally, the IL-6/STAT3 pathway was also involved in the process by which P. gingivalis and F. nucleatum promoted the proliferation of cancer cells." (PMID 33003438, 2020). "Subsequently, it was shown that SC144 binds gp130 and inhibits the activity of IL-6 and LIF, likely through binding the CHR of gp130, resulting in suppression of cancer growth in human ovarian cancer xenographs." (PMID 32765502, 2020). "Accumulating evidence suggests that TGFβ-stimulated CAFs increase the secretion of IL-6 and IL-11, which trigger GP130/STAT3 signaling in cancer cells and thus promote cancer metastasis and progression." (PMID 32972405, 2020). "Studies have shown that IL-6, EGFR, NOTCH and TGF-β1 form an oncogenic signal network in cancer initiation and progression." (PMID 32894152, 2020). "Interleukin-6 (IL-6), IL-8, transforming growth factor β (TGF-β), CXCL1, or VEGF are examples of soluble factors with pleiotropic effects that can foster cancer growth and spread." (PMID 33220234, 2020). "A740003 not only inhibited IL-10, IL-6 and monocyte chemoattractant protein-1 (MCP-1) release from macrophage, but also reduced cancer antigen presentation and cancer cell proliferation." (PMID 32280302, 2020). "TAM-derived IL6 plays a role in progression, invasion, angiogenesis, EMT, immune cell infiltration, and cancer stem cell (CSC) development and maintenance, through multiple unexplored molecular mechanisms." (PMID 32219066, 2020). "ZEB1 enhances IL-6 release and activates STAT3, which results in an increased proliferation potential of cancer cells." (PMID 32488850, 2020).
cancer (continued). "Among these, a pivotal role is played by IL-6 and TGF-β as inducers of GMT and cancer growth, IL-10 as a modulator of immune response and the chemoattractant IL-8 as a promoter of GBM motility." (PMID 33081024, 2020). "In murine models of cancer cachexia, the secretion of pro-inflammatory cytokines by WAT, such as TNFα and IL-6, has been observed." (PMID 32660156, 2020). "Chronic inflammation including cancer increases the monocyte count by the secretion of various cytokines such as TNF-α, IL-1, and IL-6." (PMID 32552873, 2020). "Oligo-Fucoidan can attenuate the negative effects of etoposide (ETO) chemotherapy that promotes IL-6 and MCP-1/CCL2 production in aggressive HCT116 cancer cells which activate Stat3 and Stat6 signaling, respectively." (PMID 32059469, 2020). "Andrographolide can stifle both constitutively activated and IL-6-induced phosphorylation of STAT3 and, consequently, its nuclear translocation into cancer cells." (PMID 32545187, 2020). "In particular, interleukin 6 (IL-6) and leptin, which are closely related to the mass of white adipose tissue (WAT), are known to activate STAT3 in cancer cells or tissues." (PMID 32722030, 2020). "Markedly up-regulated IL6 after knocking-down of UBC9 activated the expression of CD44, which was a prominent marker of cancer stem cells." (PMID 33244139, 2020). "Out of those, Ruxolitinib, Dasatinib and Siltuximab that target JAK, SRC/ABL, and IL-6 respectively, have been approved by FDA for cancer therapy." (PMID 32972405, 2020). "A large spectrum of growth factors, cytokines, and chemokines has been demonstrated to promote or to initiate PAH and cancer, including platelet-derived growth factor (PDGF) and interleukin 6 (IL-6)." (PMID 33036472, 2020). "Adipocytes communicate with surrounding cells by secreting pro-inflammatory cytokines (IL-6, IL-1β, and TNF-α) and MMPs, which modulate cancer metabolism." (PMID 33322132, 2020). "Such as for the best known and longer studied homologue cytokine IL-6, a prominent role is emerging for IL-30 in tumorigenesis, given its ability in shaping the TME and cancer stem cell niche, in which myeloid cells are critically involved." (PMID 32143355, 2020). "Our study has established a new molecular link between SMARCB1 and IL6 in the immune reaction and highlights SMARCB1 as a key molecule in the development of treatment for inflammation-related diseases, including cancers." (PMID 32492816, 2020). "In ovarian cancer cells, curcumin inhibited the lysophosphatidic acid-induced secretion of IL-6 and IL-8 by inhibiting STAT3 phosphorylation, resulting in reduced cancer cell motility." (PMID 32731620, 2020). "The MCT-1/miR-34a/IL-6/IL-6R signaling axis was revealed to promote EMT and cancer stemness in triple-negative breast cancer." (PMID 32268506, 2020). "Several proinflammatory cytokines, such as IL-6, IL-1β, TNF-α, facilitate the cancer progression by recruiting and activating MDSCs at the sites of the next metastases." (PMID 33123472, 2020). "Interferon gamma, IL-6, TNFα, and TRAIL are all secreted signaling molecules that have prominent roles in the regulation of cell death in various cell types, including cancer cells in addition to their immune regulatory functions." (PMID 33375357, 2020). "Among them, IL-6 and IL-11 are secreted interleukins activating STAT-3-dependent survival and spreading of metastatic CRC cancer cells." (PMID 33553157, 2020). "As one of the most significantly changed cytokines, IL6R caught our attention, since it has been reported that IL-6/IL-6R complex plays a pivotal role in the JAK-STAT pathway during immune responses and cancer progression." (PMID 31903134, 2020). "The culmination of inflammatory mediators (Stat3, IL-6, TNF-alpha) guides to an immuno-suppression and following progression of cancer." (PMID 32570802, 2020).
cancer (continued). "The NF-κB pathway and its target genes that include cytokines (TNFα, IL1, IL6, and IL8) were crucial for cell survival and proliferation, anti-apoptosis, EMT, and metastasis in cancers." (PMID 32883003, 2020). "Once educated by cancer cells, BM-MSCs secrete CXCL1, CXCL2, SDF1, IL-6, IL-8, TGFβ and microvesicles containing miRNA, such as miRNA-21 and miRNA-34a, all factors implicated in BC survival, progression and chemo-resistance." (PMID 32850459, 2020). "We have previously reported that hWJSC-CM contains significantly higher levels of interleukins and adhesion molecules like IL-1a, IL-6, IL-8, HGF, SCF, and MCP-1 that regulate cancer cell death and modulate the immune system." (PMID 32377203, 2020). "We recently reported IL-5, IL-10, IL-6, CxCL-10, and TGF-β elevation in both participants with EpKS and EnKS when compared to KSHV-infected asymptomatic controls prior to cancer therapy." (PMID 32560243, 2020). "Intriguingly, it has been elucidated that STAT3 can be activated by IL-6 through Janus kinase 2 (JAK2), and IL-6/JAK2/STAT3 has been implied as a crucial accelerator for tumorigenesis and EMT in many cancer types, including HCC22." (PMID 31949128, 2020). "During the progression of carcinogenesis, MSCs are recruited to the TME by growth factors, cytokines and chemokines, such as IL‐6, IL‐1β, TGF‐β1, EGF, PDGF, TNF‐α and SDF‐1α, secreted by cancer cells and stomal cells." (PMID 32588948, 2020). "Leptin, IL-6, and TNF-α are proinflammatory cytokines produced by adipose tissue and that are also increased in cancer, while adiponectin protects against tumorigenesis and its serum levels are usually decreased in cancer patients." (PMID 32604970, 2020). "IL6 induces Stat3 phosphorylation by JAK, which promotes its nuclear localization and target gene expression under various atrophic conditions including cancer cachexia and sepsis." (PMID 32635462, 2020). "IL-6,10/JAK-STAT3 pathways are found in many carcinomas, and their hyperactivation was generally related to unfavorable clinical prognosis." (PMID 32508531, 2020). "Inside carcinoma cells, Gal-9 up-regulates the expression of a variety of pro-inflammatory cytokines which are critical for MDSC differentiation, including IL-1β and IL-6." (PMID 32632113, 2020). "Inflammatory cytokines, such as interleukin-6 (IL-6), IL-1, and tumor necrosis factor-alpha (TNF-α), can promote cancer progression." (PMID 31766230, 2019). "Several studies have highlighted the effect of the IL-6/Janus Kinase/Signal transducers and activators of transcription (JAK/STAT) signaling pathway on cancer initiation and progression." (PMID 31798539, 2019). "Paracrine IL-6, possibly together with these factors, favor activation of the MEK signaling pathway in cancer cells." (PMID 30631150, 2019). "Increased IL-6 was found in the supernatant of isolated CAFs, which suppressed HIC1 expression in cancer cells and promoted BrCA cell proliferation." (PMID 31795965, 2019). "Inflammatory mediators such as tumor necrosis factor-alpha (TNF-α), Interleukin-6 (IL-6), Interleukin-10 (IL-10) and transforming growth factor-beta (TGF-β) play important roles in tumorigenesis and the development of cancer in different entities." (PMID 31077235, 2019). "In other studies, numerous blood parameters were investigated as potential inflammatory biomarkers, including elevated serum IL-6 and CD152 concentrations, which are correlated with poor outcomes in patients with cancer." (PMID 31339548, 2019). "Being a regulatory interface between IFN-gamma and IL-6, IDO1 promotes a pro-inflammatory response that plays a role in cancer neovascularization, by enhancing new blood vessel development." (PMID 30806743, 2019). "IL6, secreted by TAMs, binds to the IL6 receptor (IL6R) on the cancer cell surface to phosphorylate STAT3 (pSTAT3)." (PMID 30927925, 2019).